RN7SL32P (RNA, 7SL, cytoplasmic 32, pseudogene)
Gene: Miscellaneous RNA gene on chromosome 2 (233,205,199 to 233,205,479, forward strand). Ensembl gene ENSG00000263941.
Homologues: Orthologues: macaque Metazoa_SRP (45% identical). Paralogues in human: RN7SL279P (79% identical), RN7SL850P (76% identical), Metazoa_SRP (75% identical), RN7SL377P (75% identical), Metazoa_SRP (74% identical), Metazoa_SRP (73% identical), RN7SL48P (72% identical), Metazoa_SRP (72% identical), RN7SL716P (70% identical), RN7SL202P (70% identical), RN7SL356P (69% identical), RN7SL155P (69% identical), and 706 more.